HLF (HLF transcription factor, PAR bZIP family member)
Diseases named in the same sentence as HLF in open-access papers (continued):
Sharing a sentence is not in itself a finding about the gene and the disease.
tumor (continued). "Among these 20 common genes, the expression levels of CDK20, AKAP7, AZIN2, LIX1L, OSCP1, and SLFN12 were upregulated, while HLF was downregulated in TC-PD-L1+ tumours (Pattern 3 and Pattern 4)." (PMID 29921949, 2018). "In acute B-lineage leukemia, HLF gene translocating to fuse with the E2A gene drives tumor development." (PMID 28545024, 2017). "When Ad-hLF was administered to the tumor-bearing mice, the levels of serum IFN-γ and IL-2 were significantly increased and were close to the levels in the normal group (P<0.05)." (PMID 24520300, 2014). "Natural killer (NK) cell activity and the number of CD4+ and CD8+ T lymphocyte cells in the peripheral blood of tumor-bearing mice were increased by Ad-hLF." (PMID 24520300, 2014). "In the present study, in which tumor-bearing mice were treated with Ad-hLF, the level of serum IL-2 was increased, which indicates that hLF activates NK cells." (PMID 24520300, 2014). "Treatment with Ad-hLF increased the levels of serum interferon-γ, serum interleukin-2 (IL-2) and tumor necrosis factor-α, and decreased the levels of serum IL-4 in tumor-bearing mice." (PMID 24520300, 2014). "In conclusion, hLF inhibits the growth of U14 solid tumors by modulating the immune response of tumor-bearing mice." (PMID 24520300, 2014). "Despite finding that the HLF/TFEB axis drives immune evasion via PD-L1, the regulation of HLF/TFEB axis on tumor immunity may have other mechanisms." (PMID 40779629, 2025). "For example, the HLF/TFEB axis–mediated autophagy may not only support tumor cell survival and proliferation but also alter tumor antigen presentation, immune cell trafficking, and effector immune cell function in the tumor microenvironment (TME)." (PMID 40779629, 2025). "We then performed orthotopic injection of HLF-depleted 786-O cells in NSG mice and found that loss of HLF promoted lung metastasis without affecting primary tumor growth." (PMID 40473600, 2025). "In addition, hepatic leukemia factor (HLF), an oncoprotein in TNBC, regulates the secretion of growth factor 1 (TGF-β1) by tumor-associated macrophages (TAMs) by promoting IL-6." (PMID 39273650, 2024). "The tumor suppressor role of HLF was validated in ATC cell lines through in vitro experiments." (PMID 39872516, 2024). "The up-regulation of EMT pathway in the HLF-knockdown group may explain its role as a tumor suppressor in ATC." (PMID 39872516, 2024). "In addition to this, we discovered that the expression of the HLF gene was significantly elevated in THYM tumor tissues in comparison to normal tissue samples." (PMID 38711550, 2024). "In our analysis, HLF is downregulated in higher grade tumours." (PMID 37400829, 2023). "Previous experiments have already demonstrated the anti-tumor roles of HLF and SELENBP1 in LUAD." (PMID 35205284, 2022). "In NSCLC, HLF expression was reported to be decreased in tumor tissues." (PMID 35205284, 2022). "Notably, among the 5-gene signature, only the gene HLF is involved in tumor immunity and the gene ST3GAL5 is involved in tumor invasion, migration, and proliferation." (PMID 31998783, 2020). "Humanized M860 with increased binding affinity for hFcγRIIa may further enhance the efficiency in facilitating the anti-tumor potential of low dose hLF in vivo." (PMID 31600968, 2019). "In this study, we demonstrate that M860, a monoclonal antibody against human LF (hLF), could significantly increase the anti-tumor potential of low dosage hLF by forming LF-containing immune complex (IC)." (PMID 31600968, 2019). "HLF is one hypoxia response regulator, and its transcriptional role varies among tumor types." (PMID 30445744, 2018). "Moreover, the expression levels of ATF3 in CRC correlated with the expression of its target genes, such as CEACAM1, DUSP14, HDC, HLF and ULBP2, which are required for tumor cell invasion and proliferation and are robustly linked to poor prognosis in CRC." (PMID 28402947, 2017). "In conclusion, the immune response of tumor-bearing mice was upregulated by hLF." (PMID 24520300, 2014).
tumor (continued). "Finally, vascular endothelial growth factor (VEGF) expression in tumor tissues was downregulated by Ad-hLF." (PMID 24520300, 2014). "hLF increased the activity of NK cells and rescued the balance of serum cytokines in tumor tissue." (PMID 24520300, 2014). "After NK cell activity is promoted by hLF, NK cells release full granzymes to kill tumor cells." (PMID 24520300, 2014). "The results demonstrated that the number of CD4+ and CD8+ T lymphocyte cells in the peripheral blood of tumor-bearing mice treated with Ad-hLF significantly increased compared with that of the control group (P<0.05) and was near to that of normal mice (P>0.05)." (PMID 24520300, 2014). "The activity of tumor-killing NK cells was upregulated by hLF." (PMID 24520300, 2014). "Therefore, we can suggest that abnormal HLF expression may alter tumor immunity in a variety of human cancers and affect the successful treatment of cancer patients." (PMID 38711550, 2024). "We found that the number of CD4+ and CD8+ T cells in the peripheral blood of tumor-bearing mice treated with Ad-hLF significantly increased compared with that of the control group, which suggests that Ad-hLF increases the expression of CD4+ and CD8+ T cells and may activate them." (PMID 24520300, 2014). "Analysis of data from 33 common cancers in the TCGA database revealed that the genes HLF, HPCAL1, and NUPR1 exhibit significant differential expression between tumor and normal tissues in LUAD and several other cancers." (PMID 40421217, 2025). "Among them, ARL14 was significantly upregulated in tumor samples, while ZDHHC11B and HLF were downregulated." (PMID 39901294, 2025). "Recent studies also revealed that hepatic leukemia factor (HLF) can promote chemoresistance in TNBC by inhibiting ferroptosis through the regulation of the IL-6/TGF-β1 signaling axis, ultimately facilitating tumor progression and metastasis." (PMID 39759144, 2024). "Regarding gene amplification, EWSR1, FLT3, GPC3, HIF1A, HLF, and MEN1 have been reported in CaPa and other neoplasias as well." (PMID 38397997, 2024). "So far, no studies have shown that these seven genes (IGHG2, PODXL2, LRRC17, GABRA3, SCUBE3, HLF and RFLNB) are directly related to pyroptosis in tumor cells." (PMID 36155774, 2022). "Subsequently, hepatic leukemia factor (HLF) promotes resistance to ferroptosis in TNBC cells via GGT1, ultimately promoting malignant tumor progression." (PMID 35958626, 2022). "Subsequently, HLF promotes the ferroptosis resistance in TNBC cells via GGT1 and ultimately facilitates the malignant tumor progression." (PMID 34991659, 2022). "The results showed that compared with HSKMC, PODXL2, LRRC17, GABRA3, SCUBE3, and RFLNB were highly expressed in tumor cells, while IGHG2 and HLF were low expressed." (PMID 36155774, 2022). "We further discovered the possible role of tumor suppressors DLC1 and HLF in AURKB-mediated adverse outcome of LUAD." (PMID 33612479, 2021). "After mice were treated with Ad-hLF, we detected VEGF expression in tumor tissues using immunohistochemistry." (PMID 24520300, 2014). "For example, transcripts for suppressors TFAP2B AP-2 α/β, HLF (↓7.951 fold) and EDN3 (↓5.932 fold) were decreased in tumor cells compared to basal cells." (PMID 22280838, 2012). "In fact, cantharidins, a class of potential anti-tumor agents, are thought to induce apoptosis by E4BP4-mediated inhibition of the antiapoptotic activity of HLF." (PMID 21975218, 2011). "In addition, HLF drives TFEB-induced programmed death ligand 1 expression in human tumors and governs tumor immune evasion in a CD8+ T cell–dependent manner." (PMID 40779629, 2025). "Due to the lack of a reliable HLF antibody, we analyzed HLF mRNA levels in these paired tissues and observed a decrease in HLF expression in ccRCC tumor samples." (PMID 40473600, 2025).
tumor (continued). "The GEPIA2 database also revealed that whereas the expression of the HLF gene was dramatically downregulated in malignant tissues of ACC, CESC, GBM, OV, SKCM, and UCS, it was significantly upregulated in tumor tissues of patients with THYM compared to normal samples." (PMID 38711550, 2024). "HLF expression was shown to be lower in tumor tissues from a variety of malignancies when compared to normal tissues." (PMID 38711550, 2024). "In TNBC, hepatic leukemia factor (HLF) transactivated gamma-glutamyltransferase 1 (GGT1) promote the ferroptosis resistance and interactive dialogue between TNBC cells, and TAMs promotes sustained activation of HLF in tumor cells through the IL-6–TGF-β1 axis." (PMID 37681908, 2023). "Interestingly, several HBV replication enhancers, for example, HLF and JUN appeared to be up-regulated in the PHH and the most differentiated HCC cells of the same tumor." (PMID 34290079, 2021). "Interestingly, in this research, two tumor suppressors (DLC1 and HLF) were both found to be closely correlated with AURKB and AURKB-associated differentially expressed miRNAs and hypermethylation." (PMID 33612479, 2021). "Compared with the negative controls, tumor growth was inhibited by hLF and mice lifespans in the Ad-hLF-treated group were prolonged to reach the levels of the CTX-treated group." (PMID 24520300, 2014). "Both HLF and NFIL3 share the same DNA binding motif and are involved in regulation of circadian rhythms, cell death, and drug metabolism, with HLF acting as a transcriptional enhancer (oncogene) and NFIL3 as a transcriptional repressor (and sometimes tumor suppressor)." (PMID 40723261, 2025). "Conversely, HLF overexpression decreased the probability to develop tumors in lungs when we counted the percentage of lung tumor formations, and decreased lung metastatic tumor signal as well as circulating tumor cells (CTCs) in blood without affecting primary tumor growth." (PMID 40473600, 2025). "We investigated the changes in immune cell infiltration that occurred in samples that showed differences in HLF expression in order to determine whether or not HLF expression was connected with the microenvironment of the tumor in a number of different types of cancers." (PMID 38711550, 2024). "Experimental design: Eight novel candidate markers, COL4A6, CYBA, TCAF1 (FAM115A), HLF, LINC01341 (LOC149134), LRRC4, PROM1, and RHCG, were selected from Illumina Infinium HumanMethylation450 BeadChip analysis of 21 tumor (T) and 21 non-malignant (NM) prostate specimens." (PMID 28052017, 2017).
cancer (36 papers, 2012 to 2026). A tumor composed of atypical neoplastic, often pleomorphic cells that invade other tissues. "Considering that CSCs have been found to be closely associated with the resistance of cancer to pharmacotherapy, we next investigated the correlation between HLF expression and gemcitabine response in GBC cells." (PMID 40779629, 2025). "To unravel the molecular processes of the HLF gene in cancer, we explored the association of HLF expression with prognosis, genetic changes, the immunological microenvironment, gene function, and drug sensitivity of cancer patients." (PMID 38711550, 2024). "Our findings demonstrated that HLF expression was downregulated in various human cancers and this dysregulation was associated with overall survival, implying that HLF may be a prognostic biomarker for certain malignancies." (PMID 38711550, 2024). "Furthermore, the results also unveiled that among studied cancers, expression of the HLF gene was strongly associated with immune infiltration in THCA." (PMID 38711550, 2024). "However, it is still unclear whether the HLF gene is implicated in the etiology of cancers and could be regarded as a possible target and a crucial mediator in a number of human cancers via a shared signaling mechanism." (PMID 38711550, 2024). "In summary, we believe that HLF expression in cancer tissues and the number of CTCs can be used as effective biomarkers for predicting the prognosis of LUAD, which plays an important role in clinical diagnosis and prognosis judgment." (PMID 40124619, 2025). "Combining computational predictions with experimental validation will provide a comprehensive understanding of hLf’s therapeutic potential in modulating apoptosis and overcoming cancer-related resistance mechanisms." (PMID 40076649, 2025). "This highlights the multifaceted role of HLF in the metastatic process and suggests potential therapeutic targets for cancer treatment." (PMID 40473600, 2025). "In a bioanalysis study, HLF was found to be downregulated in pan-cancer malignant tissues and was related to apoptosis, cell cycle, EMT, and immunological infiltration." (PMID 40124619, 2025). "Together, HLF loss decreases LPXN expression, enhancing the integration of collagen stiffness and the actin cytoskeleton through paxillin, ultimately promoting cancer cell migration." (PMID 40473600, 2025). "HLF, is a member of the bZIP transcription factor family (PAR bZIP), and is closely linked to cancer progression." (PMID 40236774, 2025). "Dysregulation of HLF has been observed in various cancer types, with its role varying depending on the biological context, functioning as either an oncogene or a tumor suppressor gene." (PMID 40421217, 2025). "We utilized the data from the TCGA dataset to perform a pan-cancer analysis of the HLF gene in this research." (PMID 38711550, 2024). "Second, we only relied on in-silico analyses; therefore, both in vivo and in vitro experiments are crucial to elucidate the specific mechanism of action of the HLF gene in progression and development of human cancers." (PMID 38711550, 2024). "Then, we investigated the effect of the abnormal expression of the HLF gene on the OS outcome of cancer patients." (PMID 38711550, 2024). "As a result, we utilized multiple databases to illustrate the potential roles of HLF in diverse types of cancers." (PMID 38711550, 2024). "To shed light on mechanisms in which abnormal expression of the HLF gene participates in cancer progression and development, we first investigated the protein partners of the HLF gene." (PMID 38711550, 2024). "For instance, HLF gene was down-regulated in COAD and LUAD, and in both cancers, lower expression was associated with worse survival of the patients (i.e., it was “suppressor-like”)." (PMID 38807223, 2024).
cancer (continued). "According to our findings, reduced HLF expression drives cancer growth, and it has the potential to be identified as a vital biomarker for use in prognosis, immunotherapy, and targeted treatment of a range of malignancies." (PMID 38711550, 2024). "Heterogeneous distribution of CRGs was observed in cancers: clock control genes such as HLF and RORs were lowly expressed in most tumors, while core clock genes such as TIMELESS and NPAS2 were highly expressed." (PMID 36895015, 2023). "Among 7912 samples across 18 cancer types, we interestingly observed that the majority of the clock control gene, such as HLF, KLF10, FBXL3, TEF, RORs (RORA, RORB, RORC), and NR1D2, are down-regulated in a wide range of cancers." (PMID 36895015, 2023). "Increased expression levels of HLF, shown to promote cell-cycle progression in various cancers, ITGA2, MUC1, and DPY19L1 have also been proposed to confer prognostic value for the survival of patients suffering from LUAD malignancies." (PMID 36551790, 2022). "Previous studies showed that when HSA was fused to hLF, it exerted better bioactivity in cancer cells than the unmodified hLF." (PMID 34572270, 2021). "Overall, due to similar cell selectiveness, hLf, bLf, and their derived peptides have been tested and recognized to exert pivotal role in cancer prevention and treatment." (PMID 32183434, 2020). "Numerous studies about the effects of lactoferrin (LF) using human lactoterrin (hLF) and bovine lactoferrin (bLF) on growth of various cancer types were conducted." (PMID 29381751, 2018). "From this list, 8 novel top candidate genes were selected based on their display of highly cancer-specific hypermethylation over multiple adjacent promoter-associated DMCs: COL4A6, CYBA, HLF, LINC0134 (LOC149234), LRRC4, PROM1, RHCG, and TCAF1 (FAM115A)." (PMID 28052017, 2017). "The anti-cancer potential of hLf was investigated on the B16-F10 melanoma cells, and it was observed that treatment with Lf inhibited colonization of the tumour in the lungs." (PMID 26016555, 2015). "We observed decreased BRG1 levels corresponding to increased expression of HLF in the cancer lines, whereas a very minor effect was observed in normal cells, suggesting that BRG1-HLF regulation may be more specific to cancer cells." (PMID 40473600, 2025). "We acknowledge that additional pathways may also play a role in HLF-mediated metastasis regulation in ccRCC and that HLF signaling pathways vary across different cancer types." (PMID 40473600, 2025). "Targeting these domains, hLf may enhance the apoptotic response, particularly in cancer cells where XIAP is often overexpressed." (PMID 40076649, 2025). "Several databases were used to assess HLF expression in the TCGA cancer samples." (PMID 38711550, 2024). "Despite past research linking HLF mutations to cancer development, no pan-cancer analyses of HLF have been published." (PMID 38711550, 2024). "In our previous studies, hLF was the only material that could induce such an in vitro vascular network and any other attempts using cancer cell lines have been unsuccessful." (PMID 33387197, 2021). "Interestingly, Zhang and colleagues showed that the restoration of hLf gene expression through the use of a methyltransferase inhibitor impaired cancer cell growth and metastasis in a model of oral squamous cell carcinoma." (PMID 32183434, 2020). "HLF is an output regulator of circadian rhythms and is aberrantly expressed in human cancers, and our results suggested that it might be related to a cell death program." (PMID 28402947, 2017). "Human lactoferrin (hLF) is a multifunctional glycoprotein that inhibits cancer growth." (PMID 24520300, 2014). "According to the findings, cancer patients with an overexpression of the HLF gene may be resistant to CAL-101 and Navitoclax but responsive to Paclitaxel, Dasatinib, Docetaxel, AZ628, Z-LLNle-CHO, WH-4-023, Bortezomib, Bleomycin (50 μM), 17-AAG, MLN4924, Vinblastine, YM155, Vinorelbine, CI-1040." (PMID 38711550, 2024).